TLR9 (toll like receptor 9)
Diseases named in the same sentence as TLR9 in open-access papers (continued):
Sharing a sentence is not in itself a finding about the gene and the disease.
infection (continued). "Three of ten human toll-like receptors (TLRs), TLR2, TLR4, and TLR9, have been reported to play roles in the recognition of T. gondii, course of infections with this parasite, and also in pregnancy progression and disorders." (PMID 23161283, 2013). "For the first time, out findings provide a clue for exploring the effects of TLR9/IFN-γ pathway on the development of TB beyond controlling of infection acquisition." (PMID 24176007, 2013). "Even more striking was the observation that during the first 48 h post-infection, TLR9−/− infected mice showed severe impaired mobility, with a significant number of animals being humanely sacrificed as a result." (PMID 23936560, 2013). "The most unexpected results came from the dramatic reduction of the capacity of F4/80+CD11b+ and F4/80lowCD11b+ populations to respond to TLR9 agonist during the infection." (PMID 23650544, 2013). "The percentage of F4/80lowCD11b+ cells able to respond to TLR9 agonist after infection was reduced by ∼70%." (PMID 23650544, 2013). "In conclusion, here we showed that TLR2 and TLR9 expression are differently regulated in DC, macrophage and monocyte lineage during the infection." (PMID 23650544, 2013). "Using a mouse model of malaria infection, the same authors showed that the TLR9 response is particularly important in early infection to produce dendritic cell-derived pro-inflammatory cytokines although other mechanisms are required for IL-1β secretion." (PMID 23046548, 2012). "Collectively, these results indicate that allicin treatment at 9 mg/kg promoted expansion of matured DCs and enhanced TLR9-mediated innate immune activation on day 5 during P. yoelii 17XL infection." (PMID 22873687, 2012). "Collectively, to date, the analysis of different mice strains lacking one or multiple TLR pathways demonstrated that TLR2, TLR4, TLR7, and TLR9 play a role in the resistance to infection with T. cruzi, with a degree of redundancy between them." (PMID 22496959, 2012). "The authors found an earlier but transient induction of this cell population by the administration of the combination of TLR9 plus TLR2 agonist concomitantly with the infection." (PMID 21869919, 2012). "The reactivity of peritoneal macrophages from the mice infected with lethal strain P. y 17XL or non-lethal strain P. y 17XNL were enhanced to pRBC lysate, and TLR2, TLR4, and TLR9 agonists at one, three and five days post-infection." (PMID 22463100, 2012). "Authors suggest that TLR9 has a primary role in the MyD88-dependent induction of IL12/IFNγ synthesis during infection." (PMID 21869919, 2012). "Together these results indicate that TLR4, as previously shown for TLR2 and TLR9, also contributes to resistance during the acute phase of infection in B6 mice." (PMID 22496959, 2012). "Like the response of macrophages to pRBC lysate, macrophages from P. yoelii 17XL- or 17XNL-infected mice responded to TLR2, TLR4, and TLR9 agonists much more strongly than macrophages from nRBCs-injected mice at one and there days post-infection." (PMID 22463100, 2012). "As antibody-dependent immunity is considered essential during blood-stage malaria infection, particularly for the resolution of the chronic stage of infection, we tried to explain antiparasite immunity with known TLR9 effects on antibody responses." (PMID 22096530, 2011). "In this study, we attempted to further examine the role of TLR9 in a Plasmodium chabaudi chabaudi (PcAS) infection model." (PMID 22096530, 2011). "Seven days post infection, the increase of TLR9 (+) cells was observed in both groups of mice given probiotic bacteria (Lc-S and Lc-S-Lc), but not in the infection control (S group), comparing with the untreated control group (C)." (PMID 21813005, 2011). "When particular cell types were analyzed by flow cytometry, it was found that after infection, TLR-9-/- mice had a higher percentage of CD8+ T cells in the lung, and both strains of mice had a reduction in B cells." (PMID 21810214, 2011).
infection (continued). "Analysis of MyD88−/−, TRIF−/−, TLR4−/−, and TLR9−/− mice revealed that TLR4- and TLR9-signaling was essential for immunopathology following C. jejuni-infection." (PMID 21698299, 2011). "Overall, the fact that expression of IFN-β was unimpaired in TLR2, TLR4 and TLR9 KO BMDM during infection strongly indicated that Brucella- or its DNA-induced IFN-β expression occurs mostly independent of TLRs." (PMID 21829705, 2011). "In plasmacytoid dendritic cells, infection of EBV activates TLR9 signaling pathway leading to IFNα production, and promotes activation of NK cells and IFNγ-producing CD3+ T cells." (PMID 21429244, 2011). "For primary infections, these studies have demonstrated an essential role of innate and adaptive immunity, including TLR9 mediated recognition by DC, the complement system, NK cells, type I and II IFNs, B cells, CD4 T cells and CD8 T cells." (PMID 20300179, 2010). "Our approach was different because we administered TLR-9 agonists (CpG-ODN) before infection, in an attempt to prevent hemorrhage-induced MSSA PN, and CpG-ODN treatment decreased the mortality as well as restoring the transcriptional activity of DCs." (PMID 20949109, 2010). "It is of interest that human cell lines expressing TLR9, permissive to infection by both coxsackievirus and adenovirus receptor (CAR)- and CD46-interacting Ad serotypes, showed a preferential activation of TLR9-mediated signaling by CD46-interacting serotypes." (PMID 21994609, 2010). "We found that the 3d mice are highly susceptible to infection with T. gondii, suggesting the possibility that the combined action of TLR3, TLR7 and TLR9 is critical for host resistance to infection with T. gondii." (PMID 20865117, 2010). "Taken together, these data reveal a role for TLR9 in the immune response to opioids during M. tuberculosis infection and provide an important example of TLR9 in host resistance to infection." (PMID 20174568, 2010). "TLR9 recognition of the MCMV genome CpG motif was shown to be critical for type I IFN production soon after infection, and for early NK cell activation." (PMID 21994556, 2009). "Both human and murine DC are activated by blood stage parasites in a TLR9 dependent manner, which is possibly mediated by hemozoin derived from infection with the human parasites." (PMID 18612394, 2008). "It is also possible that the bone marrow functions as a reservoir of granulocytes with an increased expression of TLR9, ready to be discharged in case of an infection." (PMID 17328813, 2007). "The cooperative action of TLR2 and TLR9 appears to be essential for controlling certain infections." (PMID 40460068, 2025). "TLR9-deficient mice exhibit increased lesion size and parasitic burden, which is directly associated with a lower frequency of IFN-γ-producing CD8+ T cells during infection." (PMID 40460068, 2025). "Could be TLR9 important for maintaining selective permeability of epithelial-CNS barriers and/or controlling infections?" (PMID 40460068, 2025). "While the roles of a few isolated receptors (including TLR2, TLR4, and TLR9) have been explored, the relative contributions of these and other TLRs to the host’s overall ability to control infection, as well as the potential interactions between these receptors, remain poorly understood." (PMID 40248691, 2025). "Furthermore, the copy munber of mtDNA bound by red blood cells via surface TLR9 increased during bacterial infection, correlating positively with the severity of the infection." (PMID 40046178, 2024). "Furthermore, we found that RA pretreatment significantly increased the protein expression level of TLR9 and inhibited the protein expression levels of p-p65 and p-IκB-α compared to the SE infection control group." (PMID 39456517, 2024).
infection (continued). "Analysis of IL1b and IL10 expression revealed that infection of wild-type mouse macrophages NR-9456 with S. epidermidis 1457-M10 and 1457ΔatlE induced a strong IL1b expression, which was slightly lower after infection of TLR9−/− mouse macrophages." (PMID 39567551, 2024). "The elevation of erythrocyte-bound mtDNA during infection, coupled with its correlation with infection severity, suggests that monitoring the copy numbers of mtDNA bound to red blood cells via TLR9 could serve as a novel indicator for infection surveillance." (PMID 40046178, 2024). "In situations such as infections or vaccinations, plasmacytoid dendritic cells may be activated via TLR9 to produce IFNα." (PMID 38659975, 2024). "In this study, we want to further explore whether the copy number of mtDNA bound by red blood cells through TLR9 can become a new indicator of infection monitoring." (PMID 40046178, 2024). "Since infection with LdCen−/− enhanced TLR-9 expression compared to LdWT infection, we investigated whether the TLR-9 mediated downstream signaling is also altered in LdCen−/− infected DCs." (PMID 37111420, 2023). "Neither association nor infection significantly influenced the expression of TLR9 mRNA, which was comparable in all groups." (PMID 38003758, 2023). "In addition, the expression levels of TLR2 and TLR9 in fish serve as indicators of its health status and its ability to defend against the viral pathogens’ infection." (PMID 38003793, 2023). "Overall we noticed a dramatic increase in TLR9 level with increasing time points post infection." (PMID 36707891, 2023). "Therefore, in the present study, we determined the function of TLR-9 and the signaling molecules that it triggers exclusively in DCs during LdCen−/− infection." (PMID 37111420, 2023). "Likewise, infection with L. infantum activates a protective type-I interferon response and production of IL-12 through TLR-9 activation." (PMID 37111420, 2023). "These increased levels of tlr9 may have activated the innate immune system of the host, providing better preparedness for potential infection." (PMID 37370408, 2023). "A previous study has reported that Ictalurus punctatus TLR2 transcripts increased in the spleen after Ichthyophthirius multifiliis infection, but its TLR9 transcripts decreased in the spleen after I. multifiliis infection, demonstrating discrepant roles of TLR2 and TLR9 against pathogens infection." (PMID 38003793, 2023). "Additionally, TLR9 transcripts overexpressed observably in the brain, gill, and kidney at four out of seven sampling time points after infection with CyHV-2." (PMID 38003793, 2023). "TLR9 is constitutively expressed within the endosomes of B Cells and pDCs, though additional myeloid subtypes have been found to express TLR9 when activated by immune triggers including infection." (PMID 36031601, 2022). "In accordance, blocking Tlr7 and Tlr9 signalling significantly reduced IL-6 in both wt and Ifitm3−/− cells to similar levels following infection with MCMV, suggesting that Ifitm3-mediated regulation of these responses restricts MCMV-induced cytokine production." (PMID 36075894, 2022). "Meanwhile, previous study has demonstrated that STK38 may downregulate TLR9 signaling to decrease the inflammatory cytokine production and protect the host from an inflammatory injury during infection." (PMID 36232893, 2022). "Indeed, infection model studies support the crucial role of the TLR9-MyD88 pathway in the induction of adaptive immune responses to infections, such as in fighting herpes simplex virus 1 and 2, murine cytomegalovirus, and adenovirus infections." (PMID 36611945, 2022). "TLR9 mRNA expression was significantly reduced by GLY in both mouse strains after infection." (PMID 36422579, 2022). "Although L. amazonensis failed to activate dendritic cells in both models, TLR9‐/‐ mice are more susceptible to L. amazonensis in vivo infection than WT." (PMID 35119120, 2022).
infection (continued). "Similarly, the reduction in CpG in the context of a TLR9 recognition motif suggests that TLR9 senses HPVs during infection." (PMID 36265836, 2022). "Nonetheless, this oncogene-mediated repression of TLR9 occurs after infection." (PMID 35311536, 2022). "Interestingly, other DNA viruses (e.g., Merkel cell polyomavirus, hepatitis B virus, and Epstein-Barr virus [EBV]) also interfere with TLR9 function during the maintenance phase of the infection." (PMID 36265836, 2022). "However, this ΔxerD2 knockout strain also stimulated CagA phosphorylation and TLR9 activation during infection." (PMID 35239059, 2022). "Our in vivo findings suggest that TLR2 and TLR9 modestly impact infection-induced bone loss and do not alter osteoclastogenesis in trabecular bone in vivo." (PMID 36226943, 2022). "C. neoformans DNA is capable of activating TLR9 in C57BL/6 mice during experimental infection." (PMID 33446850, 2021). "We wanted to know whether infection with EBV influences TLR9 level and maybe changes the immune response which may lead to malignant transformation." (PMID 34439137, 2021). "Some receptors, such as TLR2 and TLR9, act synergistically in helping to control the infection." (PMID 34336720, 2021). "The presence of titan cells and low levels of IFN-γ and IL-17 in the lungs indicate a susceptibility and inability of C57BL/6 mice to control the infection in absence of TLR9." (PMID 33446850, 2021). "Of interest, TLR-9 is one of the intracellular TLRs expressed by human alveolar epithelial cells that has been considered in the context of mycobacterial infection due to its capacity to sense microbial DNA and mediate protective responses against infection." (PMID 34456901, 2021). "However, TLR9 only has a role in protecting animals from MHV68 infection when MHV68 is administered from the intraperitoneal or intravenous route, not the intranasal route, possibly because TLR9 is not expressed in lung dendritic cells." (PMID 34749760, 2021). "In contrast, the infection decreased TLR9 mRNA expression in the colon." (PMID 32842482, 2020). "TLR9 signaling is essential for the early cytotoxicity of NK cells during infections." (PMID 32140147, 2020). "TLR9 has been reported to regulate inflammation following infection with Aspergillus79." (PMID 33177569, 2020). "However, the level of TLR9 mRNA in the lungs of klotho KO mice was significantly decreased compared with that of klotho WT mice at 3 days post-infection." (PMID 33329595, 2020). "Thus, we decided to evaluate the in vitro infection by L. amazonensis in TLR9-/- cells in comparison with WT C57BL/6 mice." (PMID 30802247, 2019). "Future therapeutic interventions directed to mucosal activation of the mtDNA/TLR9/NF‐κB axis may help in prevention of mucosal damage, pain, and infection driven by medical devices." (PMID 30548974, 2019). "Importantly, 85% of TLR9−/− mice infected with lethal IOE survived until 60 days post-infection while all infected WT mice died between 10 and 12 days post-infection." (PMID 31134081, 2019). "As such, TLR2, TLR3, TLR4, TLR7, TLR8, and TLR9 are known to recognize EBV during infection." (PMID 31238570, 2019). "However, the TLR9-/- mice showed a slight increase in the lesion size at the peak of infection, which coincided with an increase in parasite load." (PMID 30802247, 2019). "Thus, we wondered if TLR9-/- mice would make higher levels of IFN-γ following dual infection with H1N1 + SPS3, and if so, if that would correlate with higher SPS3 bacterial loads." (PMID 30682165, 2019). "Similarly, BMDMs from TLR9-/- mice show higher iNOS expression following ex vivo infection with H1N1." (PMID 30682165, 2019). "To understand whether TLR9-/- mice are clearing the bacteria better post dual infection due to differences in their cytokine profiles, we measured the levels of different pro and anti-inflammatory cytokines." (PMID 30682165, 2019).
infection (continued). "Interestingly, the diminished IL-8 responsiveness of COPD alveolar macrophage to NTHi infection has a strong association with the carriage of TLR9 (T1237C) polymorphism instead of TLR2 (Arg753Gln), TLR4 (Thr399Ile; Asp299Gly), and TLR9 (T1486C)." (PMID 30455693, 2018). "Moreover, a recent study shows a TLR9/IFNγ-dependent activation of autoreactive T-bet+CD11c+ atypical B cells in response to P. yoelii 17XNL infection in mice." (PMID 30387712, 2018). "Although some viruses have sufficient ISS CpG motifs to stimulate TLR9 the HPV genome has the lowest CpG content among viruses with most of them in non-ISS context, in keeping with HPVs’ association with long-term stable infection." (PMID 29330557, 2018). "Furthermore, we also demonstrated here that rfd phages devoid of the scFv anti-DEC-205 on pIII also require the expression of TLR9 by the host in order to confer protection against infection." (PMID 29896197, 2018). "By detecting extracellular T. cruzi through TLR2 and TLR4 at the moment of the infection, or intracellular T. cruzi through TLR9 and TLR7, the cardiomyocytes should activate the MyD88 pathway and induce CCL5 that will focus the recruitment of cytotoxic CD8+ T cells towards the infected cell." (PMID 30067739, 2018). "Interestingly, TLR9 has also been identified as a specific sensor of RNA:DNA hybrids, a key intermediate component essential to the replication during infection." (PMID 30410483, 2018). "Although the contribution of Ehrlichia-derived PAMPs to inflammasome activation needs to be investigated, these data suggest that mitochondrial DAMPs are potential ligands for TLR9/MyD88-mediated inflammasome activation during lethal infection with LPS-negative Ehrlichia." (PMID 29049365, 2017). "Furthermore, MyD88−/− and TLR9−/− C57BL/6 mice produced significantly less IFN-γ following infection with T. brucei brucei, coinciding with impaired parasite clearance and reduced survival." (PMID 28936213, 2017). "Our study makes two important contributions; firstly, it identifies molecular mechanisms that are likely to contribute to the susceptibility of badgers to infection with bTB: specifically, no NO and low TLR9-responses." (PMID 28382943, 2017). "This response may be mediated by the intracellular Pattern Recognition Receptor (PRR) Toll-like receptor 9 (TLR9), which recognizes in vertebrates CpG unmethylated DNA as a sign of infection." (PMID 27455096, 2016). "WT and single TLR2, TLR4 and TLR9 KO mice similarly control infection in liver and spleen." (PMID 28119856, 2016). "Unlike TLR9-/-, which are more susceptible to infection, AEP-/-, CatL-/- and CatS-/- mice are as resistant to L. major infection as WT mice, suggesting that these proteases are not individually involved in TLR9 processing." (PMID 27182703, 2016). "Considering the different course of infection dynamics between CatB-/-, WT and TLR9-/-, we questioned the role of this protease in the immune response to L. major infection and if it could affect TLR9 activation." (PMID 27182703, 2016). "In the skin, upregulation was seen only for TLR9 and FoxP3 in the early stages of infection." (PMID 26465878, 2015). "Moreover, it has been shown that TLR-2 and TLR-9 are important for parasite control in the early phases of infection." (PMID 26147698, 2015). "Similarly, infection of isolated neutrophils has also shown an elevated TLR9 expression in a cagPAI-independent manner." (PMID 25945326, 2015). "In addition, type-I IFN such as IFN-α and IFN-β mRNA expression was significantly reduced in the TLR9−/− mice during infection." (PMID 25945326, 2015). "CpG properties indicating a potentially strong activation potential of TLR9 could indicate the primary immune response during infection with these diseases." (PMID 26179610, 2015). "This clearly demonstrates that MyD88 and TLR9 deficient mice have impaired immune response generation after infection with L.guyanensis, regardless of the presence of LRV virions." (PMID 24801628, 2014).